INS (insulin)
Diseases named in the same sentence as INS in open-access papers (continued):
Sharing a sentence is not in itself a finding about the gene and the disease.
Obesity (continued). "It is also required for the increase inβ-cell mass in situations of increase insulin demand (obesity,pregnancy)." (PMID 15203882, 2004). "Furthermore, literature has also indicated that BRD7 is involved in regulating glucose metabolism and insulin signalling pathways, thereby influencing processes such as obesity and embryonic development." (PMID 41510594, 2026). "Targeting PPARγ and its downstream pathways offers translational potential for the treatment of obesity and metabolic disorders by enhancing energy expenditure and insulin sensitivity, although adverse effects of synthetic agonists limit their long-term clinical use." (PMID 41596403, 2026). "ERRα, a master regulator of mitochondrial biogenesis and energy metabolism, is targeted by inverse agonists (compound 29, GSK5182) and agonists (JND003, SLU-PP-915), which show promise in ameliorating insulin resistance and promoting lipid oxidation in preclinical obesity models." (PMID 41750342, 2026). "Both interventions reduced weight, reversed obesity-induced alterations in insulin, leptin, and inflammatory factors, and decreased tumor incidence and mass, with intermittent energy restriction producing the most favorable antitumor immune and metabolic environment." (PMID 41551882, 2026). "Genetic predisposition, receptor-level alterations, and impaired intracellular insulin signaling may precede weight gain and can be further aggravated by obesity-related inflammation and lipid overload, thereby amplifying metabolic and neurocognitive risk." (PMID 41596611, 2026). "Exogenous OXM improves glycemic control and insulin secretion in both animals and humans with obesity or T2DM, although its concurrent glucagon receptor activity may attenuate its glucose-lowering effects relative to GLP-1 receptor agonists." (PMID 41575482, 2026). "In obesity, CD11c+ innate immune cells (mainly M1 macrophages and inflammatory dendritic cells) are recruited to adipose tissue and induce an inflammatory state, leading to insulin and catecholamine resistance." (PMID 41503874, 2026). "For instance, the presence of Prevotella copri and Blastocystis species, which is regarded as uncommon in individuals with obesity, was found to be a strong indicator of more favorable postprandial glucose tolerance, insulin, C-peptide (all 0–2-h iAUC), TAG (0–6-h iAUC), and visceral fat mass." (PMID 40587382, 2026). "Key mechanisms explored include adipose tissue endocrine dysfunction (contributing to the obesity paradox), hepatic insulin resistance and bile acid signaling, skeletal muscle energy crisis and wasting, and the pivotal roles of macrophage glycolytic polarization and T-cell subset imbalance." (PMID 41898434, 2026). "Additionally, these mice demonstrate resistance to diet‐induced obesity, along with improved glucose tolerance, enhanced insulin sensitivity, and reduced hepatic lipid accumulation." (PMID 41117143, 2026). "Bariatric surgery may offer long-term cancer protection for women with obesity, especially those with elevated insulin levels, highlighting the importance of metabolic profiling in treatment planning." (PMID 41490246, 2026). "Such interaction may be a potential mechanism by which lncMGC contributes to impaired insulin signaling in obesity, with attendant dysregulated adipose lipid metabolism and thermogenesis." (PMID 41532014, 2026). "Such compounds could be evaluated in animal models of obesity to assess their efficacy in modulating metabolic pathways, improving insulin sensitivity, reducing adiposity, and restoring overall metabolic balance." (PMID 41596407, 2026). "Studies have shown that intensive insulin therapy in surgical ICU patients can reduce AKI incidence; hypertriglyceridemia has been confirmed to be associated with increased risk of AKI; and obesity is an independent risk factor for AKI development." (PMID 41601879, 2026).
Obesity (continued). "Moreover, maternal circulating hepcidin levels showed a strong positive correlation with obesity‐related factors in dams, including maternal body weight, maternal fat mass, maternal leptin and maternal insulin at E13.5." (PMID 41275403, 2026). "Obesity, for example, raises blood pressure by increasing vascular resistance, while insulin resistance and high lipid levels (such as triglycerides and LDL cholesterol) promote atherosclerosis, a process that narrows and hardens the arteries, worsening hypertension." (PMID 41515261, 2026). "Experimental and clinical studies consistently demonstrate that high SUA can impair insulin signalling in the liver, skeletal muscle, and adipose tissue, while metabolic disturbances such as obesity and hyperinsulinemia further exacerbate hyperuricemia, creating a reinforcing pathological cycle." (PMID 41521685, 2026). "This is opposite to the effects of adiponectin deficiency during AL feeding or obesity and occurred without changes in insulin concentrations or sensitivity." (PMID 42313833, 2026). "We assessed the effects of daily potato fiber/sugar beet pectin supplementation (fiber, n = 19) versus maltodextrin (placebo, n = 21), both added to a high-protein diet (25E% protein, ±45% plant-based), on peripheral insulin sensitivity (IS) in adults with overweight/obesity." (PMID 41459804, 2026). "Here, we investigated whether markers of UPR activity are elevated in skeletal muscle in obesity and T2D and to what extent insulin regulates these UPR markers." (PMID 42017540, 2026). "In addition, insulin, which is also increased by obesity, increases hepcidin mRNA and protein expression in a human hepatic cell line (HepG2 cells)." (PMID 41275403, 2026). "Our data identify a role of Tent5a in enhancing insulin production, which may be involved in boosting insulin synthesis and maintaining euglycemia in obesity." (PMID 42161934, 2026). "Background/Objectives: The fern “Cyclosorus terminans” (C. terminans) or “Maiden Fern” contains interruptin A and interruptin B. This plant could attenuate obesity, insulin resistance, and fatty liver in rats fed a high-fat/calorie diet." (PMID 40284250, 2025). "Furthermore, SYR helps to manage obesity by lowering body weight and fat mass, attenuating leptin levels, enhancing adiponectin circulation, improving insulin resistance, and modulating genes involved in lipid metabolism." (PMID 41170185, 2025). "In humans, PCSK9 levels significantly correlate with the classical parameters of metabolic syndrome such as obesity, serum insulin levels, fasting blood glucose, and hypertension, whose effects on atherosclerosis progression are also independent of LDL metabolism." (PMID 39940773, 2025). "It is well established that obesity promotes oxidative stress which may contribute to adipose tissue pro-inflammatory tone and insulin resistance." (PMID 41011406, 2025). "This accumulation is consistent with early metabolic disturbances related to obesity and low-grade inflammation, where reduced amino acid clearance and altered hepatic enzyme activity accompany adipose tissue expansion, yet insulin signaling remains partially preserved." (PMID 41002949, 2025). "The authors explained that on the one hand, SIT-induced improvements on insulin action were less pronounced in individuals with obesity compared with those with normal weight, and on the other hand, 10 s interval duration was too short to stimulate substantial short-term glucose uptake." (PMID 39917538, 2025). "These primates offer the benefit of naturally developing obesity, exhibiting physiological and biochemical traits that closely mirror those seen in humans, such as body mass index, fat buildup in the abdomen, insulin resistance, altered lipid profiles, and the onset of diabetes mellitus." (PMID 39858515, 2025). "Activin E improves insulin sensitivity, increases energy expenditure, and protects from obesity." (PMID 40431415, 2025).
Obesity (continued). "Hence, restoring GIP signaling by TRZ can reduce body weight and improve the insulin sensitivity in obesity." (PMID 40498212, 2025). "Insulin could be involved in this regulatory process, as it is downregulated during fasting and upregulated in obesity, where it inhibits ghrelin production and secretion from the stomach." (PMID 40797062, 2025). "TRE demonstrates efficacy in reducing insulin levels among women with overweight or obesity." (PMID 41036194, 2025). "Overall, the cGAS‐STING signaling pathway intricately intersects with various aspects of energy homeostasis and metabolic regulation, significantly contributing to the pathophysiology of obesity, adipose tissue inflammation, and insulin resistance through multiple mechanisms." (PMID 39158380, 2025). "In the current study, we induced T2Dx by feeding a diet with 60% kilocalories from fat for 4 months, producing very mild hyperglycemia but marked obesity and hyperinsulinemia (as determined via intraperitoneal insulin tolerance test and fasting serum insulin ELISA)." (PMID 41295303, 2025). "Thus, this study provides evidence that insulin hypersecretion in an obesogenic context can promote obesity." (PMID 41009753, 2025). "Of note, 65 women with overweight/obesity had normal insulin sensitivity." (PMID 40507609, 2025). "Interestingly, there was a trend toward a significant main effect of group on serum insulin response (p = 0.06), with participants with obesity exhibiting a higher response." (PMID 40574473, 2025). "Likewise, miR-690 mimic treatment or APC-specific miR-690 overexpression improved APC maintenance in obesity, increasing the proportion of small adipocytes in eWAT and, consequently, promoting insulin sensitivity." (PMID 40912400, 2025). "Dysregulated appetite arises as a key consequence: hyperinsulinemia may enhance hunger, while impaired central insulin signaling reduces the brain’s responsiveness to satiety cues, collectively contributing to obesity progression and metabolic dysfunction." (PMID 41282294, 2025). "We examined glucose effectiveness and insulin-dependent hypoglycemic effects using biological experiments and a mathematical model in an attempt to reveal alterations in the responses in the progression of obesity." (PMID 41433229, 2025). "Furthermore, the inhibition of HIF-1α has the potential to ameliorate obesity phenotypes, such as increased insulin tolerance and adipogenesis." (PMID 39900792, 2025). "However, exceptional cases of the uncoupling of IR from obesity have been reported, for instance, the “athlete’s paradox”, namely, a higher lipid content is concomitant with increased insulin sensitivity." (PMID 41353211, 2025). "Therefore, the scope of this review is to summarize current knowledge on the impact of postbiotics on host metabolism, immunity, and endocrine function related to metabolism, specifically glucose and insulin metabolism related to obesity." (PMID 39235984, 2025). "Although this state may appear as “obesity,” insulin sensitivity is maintained, and it may represent the so-called “metabolically healthy obesity (MHO)” phenotype." (PMID 40368161, 2025). "The preservation of insulin sensitivity in Ctrp10 KO female mice is due, at least in part, to the absence of obesity-linked adipose and liver inflammation, fibrosis, and oxidative stress." (PMID 37961647, 2025). "Moreover, prepubertal MHO subjects demonstrated a significantly higher Matsuda index than pubertal MHO subjects, providing evidence of enhanced insulin sensitivity in younger individuals with obesity." (PMID 39857881, 2025). "Even though we saw obesity‐associated region‐specific increases in insulin‐stimulated BGU, the exercise intervention did not decrease BGU in these regions in neither of the co‐twin groups." (PMID 40926735, 2025).
Obesity (continued). "Proteomics data in this study demonstrated systemic downregulation of pathways and processes associated with mitochondria, impaired fatty acid metabolism, and increased insulin signalling in hypertensives, often observed in obesity-driven cardiovascular damage." (PMID 41356094, 2025). "Given the reduced insulin sensitivity in the individuals with obesity, we also examined the mRNA levels of Glucose Transporter Type 4 (GLUT4, also known as SLC2A4) gene responsible for glucose uptake in SkM, which was significantly decreased in individuals with obesity." (PMID 40127780, 2025). "In view of the rising obesity rates among people with type 1 diabetes and some study findings supporting unfavourable eating patterns with automated insulin delivery (e.g. slippage into increased snacking), attention to this matter may be required." (PMID 39560745, 2025). "GLP‐1 RAs (liraglutide, semaglutide, tirzepatide) have been approved to treat obesity and provide these effects via increased insulin release, increased insulin sensitivity, decreased gastric emptying and acting on central receptors in the central nervous system (CNS) to reduce appetite." (PMID 40184508, 2025). "Both HOMA-IR and fasting insulin trajectories varied by obesity status." (PMID 40823908, 2025). "Notably, d-allulose seemed to elicit greater improvements in insulin sensitivity in the high-sucrose obesity model compared to the HF model, suggesting a potential interaction with sugar metabolism." (PMID 40573161, 2025). "Additionally, supplementing with a mixture of one or more probiotics can enhance insulin sensitivity and reduce insulin resistance in patients with T2D or obesity." (PMID 40027477, 2025). "Studies showed that gut microbiome influenced host metabolism and obesity through multiple pathways that affected gut barrier integrity, production of metabolites and insulin resistance, epigenetic factors, bile acid metabolism, and subsequent changes in metabolic signaling." (PMID 40799936, 2025). "Elevated ADMA levels may contribute to obesity via multiple mechanisms, such as interfering with insulin signal transduction and glucose metabolism, activating CaSR to promote lipid accumulation, and disrupting hepatic lipid metabolism." (PMID 41235334, 2025). "Furthermore, exogenous administration of spexin improves insulin and glucose tolerance in rodents with diet-induced T2D and obesity." (PMID 39997710, 2025). "Obesity is manifested as the accumulation of visceral fat, abnormal structure and function of adipose tissue, leading to insulin signaling disorder, increased androgen secretion, and low-grade chronic inflammation, which further aggravate obesity, forming a vicious circle." (PMID 41384017, 2025). "While obesity inherently promotes macrophage recruitment, MH obese individuals exhibit a distinct anti-inflammatory (M2) macrophage profile facilitated by adipocyte cytokine secretion that supports insulin sensitivity and control adipogenesis." (PMID 41199351, 2025). "Moreover, unlike previous observations, we were unable to demonstrate impaired insulin-mediated suppression of plasma BCAAs in individuals with obesity." (PMID 40404819, 2025). "On one hand, it may affect patients with the metabolic syndrome phenotype, where liver steatosis is the result of obesity with hepatic insulin resistance, which impairs the ability of insulin to inhibit glucose and VLDL production." (PMID 40244110, 2025). "Multiple linear regression models adjusting for age demonstrated that the obesity group had significantly higher fasting insulin levels (β = 5.59, 95% CI: 0.43–10.76, p = 0.034) and TG/HDL-C ratio (β = 0.25, 95% CI: 0.02–0.47, p = 0.032) compared to the lean group." (PMID 41374006, 2025). "SFAs may contribute to obesity through mechanisms involving inflammation, enhanced fat storage, and insulin resistance." (PMID 39861463, 2025).
Obesity (continued). "Factors associated with a lower probability of insulin initiation included higher household income (SHR 0.94 per 28% increase, 95% CI = 0.89 to 0.98), overweight or obesity versus having a healthy BMI, older age, higher eGFR, higher HDL, and later calendar year." (PMID 40897507, 2025). "Obesity is characterized by the progressive accumulation of fat in the body, accompanied by an increased proinflammatory response and oxidative stress, which compromises insulin sensitivity." (PMID 40566527, 2025). "Therefore, we aimed to develop a cell model depicting the pathophysiological state of adipocytes in obesity by applying novel approaches (insulin, macrophage supernatant, and Tnfα) using 3T3-L1 cells." (PMID 40498013, 2025). "Therefore, obesity and increased insulin secretion are expected findings in PCOS patients compared to the control group." (PMID 40572700, 2025). "Additionally, they improve adipose tissue function, enhancing insulin sensitivity and metabolic health, which reduces obesity‐driven inflammatory signaling—a key factor in cancers such as breast, colorectal, and pancreatic cancer." (PMID 40387523, 2025). "Non-targeted plasma metabolomics was conducted to identify changes in metabolites that may help explain the improvement in insulin sensitivity and lipid levels seen in subjects with obesity that received sevelamer." (PMID 40666326, 2025). "Indeed, adipose tissue of HFD‐fed mice lacking CCL2 binding receptor (Ccr2−/− mice) exhibit reduced macrophage infiltration and inflammation, improving insulin sensitivity, glucose tolerance, and suppressing obesity." (PMID 39158380, 2025). "Therefore, data regarding the role of l-lactate in modulating macrophage responses and insulin sensitivity in obesity are inconclusive." (PMID 39198360, 2025). "For example, the degree of obesity, baseline triglyceride levels, and insulin sensitivity could modulate the lipid-lowering effects of dapagliflozin." (PMID 40430228, 2025). "The fatty liver and insulin sensitivity phenotypes of miR-30afat mice resemble metabolically healthy obesity in people, a condition characterized by normal clinical measures of metabolic function (e.g., insulin sensitivity and fatty liver) and associated with expansion of subcutaneous WAT depots." (PMID 40471675, 2025). "The increased olfactory bulb volume observed in individuals with obesity may be related to neuronal plasticity induced by alterations in metabolic hormones such as leptin and insulin." (PMID 40868460, 2025). "In rodent models, obesity is linked to impaired memory, which is thought to involve exacerbated inflammation and dysregulated insulin activity by TNF‐α disruption of insulin signaling." (PMID 39219300, 2025). "While an atherogenic diet is not sufficient in promoting the onset of genuine diet-induced obesity as a model of what we call the metabolic syndrome in humans, it does induce significant metabolic changes, as seen in the glucose- and insulin-tolerance testing we performed." (PMID 41171725, 2025). "Prior research has suggested that obesity contributes to the pathogenesis of psoriasis through mechanisms such as chronic low-grade inflammation, elevated levels of proinflammatory cytokines, insulin resistance, and broader metabolic dysregulation." (PMID 41432618, 2025). "Obesity, especially visceral fat deposition, accompanied with sarcopenia will constitute one end of the metabolic spectrum, which is characterised by increased insulin resistance." (PMID 39852391, 2025). "Similarly, impaired insulin signaling via phosphoinositide 3-kinase contributes to ATM recruitment in diet-induced obesity." (PMID 41141634, 2025). "Changes in the gut microbiota may lead to the production of different metabolites, such as stimulating insulin secretion and the release of peptide hormones that control appetite, thereby contributing to obesity." (PMID 40150457, 2025).